NDUFAB1 (NADH:ubiquinone oxidoreductase subunit AB1)
Description:
Carrier of the growing fatty acid chain in fatty acid biosynthesis (By similarity). Accessory and non-catalytic subunit of the mitochondrial membrane respiratory chain NADH dehydrogenase (Complex I), which functions in the transfer of electrons from NADH to the respiratory chain. Accessory protein, of the core iron-sulfur cluster (ISC) assembly complex, that regulates, in association with LYRM4, the stability and the cysteine desulfurase activity of NFS1 and participates in the [2Fe-2S] clusters assembly on the scaffolding protein ISCU. The core iron-sulfur cluster (ISC) assembly complex is involved in the de novo synthesis of a [2Fe-2S] cluster, the first step of the mitochondrial iron-sulfur protein biogenesis. This process is initiated by the cysteine desulfurase complex (NFS1:LYRM4:NDUFAB1) that produces persulfide which is delivered on the scaffold protein ISCU in a FXN-dependent manner. Then this complex is stabilized by FDX2 which provides reducing equivalents to accomplish the [2Fe-2S] cluster assembly. Finally, the [2Fe-2S] cluster is transferred from ISCU to chaperone proteins, including HSCB, HSPA9 and GLRX5 (By similarity).
Synonyms: ACP; SDAP; FASN2A; ACP1
Tractability: Small molecule: an approved drug acts on it; a structure with a bound ligand is known. PROTAC: ubiquitination databases record sites on it; its protein half-life has been measured.
Target class: Enzyme; Oxidoreductase
Gene: Protein-coding gene on chromosome 16 (23,581,014 to 23,596,319, reverse strand). Ensembl gene ENSG00000004779.
Subcellular location: Mitochondrion
Subcellular location (Human Protein Atlas): Mitochondria
Pathways (Reactome):
Metabolism: Complex I biogenesis; Mitochondrial Fatty Acid Beta-Oxidation; Respiratory electron transport
Metabolism of proteins: Mitochondrial ribosome-associated quality control; Protein lipoylation
Gene Ontology:
Molecular function: mitochondrial large ribosomal subunit binding; protein binding; structural molecule activity; acyl binding; acyl carrier activity; calcium ion binding; fatty acid binding
Biological process: [2Fe-2S] cluster assembly; mitochondrial large ribosomal subunit assembly; protein lipoylation; aerobic respiration; fatty acid biosynthetic process; iron-sulfur cluster assembly; mitochondrial electron transport, NADH to ubiquinone; proton motive force-driven mitochondrial ATP synthesis
Cellular component: mitochondrial [2Fe-2S] assembly complex; mitochondrial inner membrane; mitochondrion; respiratory chain complex I; iron-sulfur cluster assembly complex; mitochondrial matrix; mitochondrial membrane
Genetic constraint (gnomAD): Loss-of-function variants: 3 observed, 12.65 expected, observed/expected ratio (o/e) 0.24, 90% interval 0.11 to 0.61. The upper end of that interval is the gene's LOEUF score, 0.61, which puts it in group 2 of 6, group 1 being the genes least tolerant of losing a copy. Missense variants: 154 observed, 172.89 expected, observed/expected ratio (o/e) 0.89, 90% interval 0.78 to 1.02. Synonymous variants: 74 observed, 68.39 expected, observed/expected ratio (o/e) 1.08, 90% interval 0.9 to 1.31.
Homologues: Orthologues: chimpanzee NDUFAB1 (100% identical), rabbit NDUFAB1 (88% identical), dog NDUFAB1 (86% identical), mouse Ndufab1 (86% identical), pig NDUFAB1 (84% identical), guinea pig NDUFAB1 (83% identical), tropical clawed frog ndufab1 (66% identical), zebrafish ndufab1b (60% identical), rat Ndufab1 (57% identical), zebrafish ndufab1a (54% identical), Drosophila melanogaster ND-ACP (51% identical), Caenorhabditis elegans ndab-1 (41% identical). Paralogues in human: ZNF593 (18% identical).